TRIB1 (tribbles pseudokinase 1)
Diseases named in the same sentence as TRIB1 in open-access papers (continued):
Sharing a sentence is not in itself a finding about the gene and the disease.
coronary artery disease (16 papers, 2011 to 2025). "The results of this study suggest associations between the PON1 rs662, rs854560 and TRIB1 rs17321515, rs2954029 polymorphisms and lipid parameters in patients with coronary artery disease." (PMID 39062650, 2024). "In our study, we did not demonstrate statistically significant associations between PON1 rs662, rs854560 and TRIB1 rs17321515, rs2954029 polymorphisms and the risk of coronary artery disease in the form of unstable angina in our population." (PMID 39062650, 2024). "A recent meta-analysis reveals that the TRIB1 SNP (Rs2954029) A allele present in the 8q24 locus is positively associated with the risk of coronary artery disease (CAD) combined with stroke." (PMID 38791967, 2024). "The role of TRIB1 in macrophages has been linked to the development of macrophage-associated diseases, including coronary heart disease." (PMID 35205759, 2022). "We determined the interaction between coffee consumption and the tribbles pseudokinase 1 (TRIB1) rs17321515 variant on coronary heart disease (CHD)." (PMID 32370221, 2020). "In conclusion, our findings highlight the interactive association of coffee drinking and TRIB1 rs17321515 polymorphism on coronary heart disease in Taiwanese adults." (PMID 32370221, 2020). "Another SNP (rs2954021) located in TRIB1 gene was associated with increasing plasma TG levels and coronary artery disease (CAD) risk as well as the other three variants: rs2001945, rs2001845, and rs2001844." (PMID 31191752, 2019). "Recently, a Danish study replicated the association between another SNP rs2954029 in TRIB1 and risk of ischemic heart disease in White descent in more than 71,000 individuals." (PMID 25986010, 2015). "Recent genome wide association studies have linked tribbles pseudokinase 1 (TRIB1) to the risk of coronary artery disease (CAD)." (PMID 25811180, 2015). "In humans, TRIB1 variation has been associated with blood lipid levels and increased risk of coronary artery disease, ischemic heart disease and myocardial infarction." (PMID 24922540, 2014). "However, the results of this study indicate an association between the PON1 rs662, rs854560 and TRIB1 rs17321515, rs2954029 polymorphisms with lipid parameters in patients with coronary artery disease." (PMID 39062650, 2024). "The purpose of the present study was to evaluate the association of the PON1 rs662, rs854560 and TRIB1 rs17321515, rs2954029 gene polymorphisms with the risk of coronary artery disease in the form of unstable angina and to investigate their association with biochemical parameters in these patients." (PMID 39062650, 2024). "Because TRIB1 has previously been associated with coronary artery disease, the TRIB1-HDL-C relationship observed within our data may have a profound impact on public health." (PMID 21589926, 2011). "Previous genome-wide association studies (GWAS) have shown that the TRPS1 (transcriptional repressor GATA binding 1) and TRIB1 (tribbles pseudokinase 1) genes located on chromosome 8q23-24 are associated with the predisposition to coronary artery disease (CAD) and with plasma lipid profile levels." (PMID 40563858, 2025). "Increased TRIB1 gene expression is encountered in the coronary arteries of patients with ischemic heart disease." (PMID 38791967, 2024). "Emerging evidence indicates tribbles homolog 1 (Trib1) protein may be involved in lipid metabolism regulation and coronary artery disease (CAD) pathogenesis." (PMID 36714195, 2023). "Of these SNPs, rs964184(APOA5-A4-C3-A1) was also related with the presence of coronary artery disease in a large GWAS for coronary artery disease, although very recently also rs2954029(TRIB1) and rs264(LPL) were identified in a GWAS for coronary artery disease." (PMID 24979386, 2014).
coronary artery disease (continued). "These SNPs are located in the TRSP1 and TRIB1 genes that encode the transcriptional repressor GATA binding 1 and tribbles pseudokinase 1 proteins, respectively, which are associated with the predisposition to coronary heart disease, and with plasma lipid profile levels in different populations." (PMID 40563858, 2025). "Coronary arteriosclerosis shared 10 GWS genes with AD (BAG6, C6orf10, HLA-DQB1, HLA-DRA, HLA-DRB1, NDUFAF6, NME7, PLCG2, PRRC2A, and TRIB1), while myocardial infarction shared three genes with AD (HLA-DRA, PHB, and RP11-81K2.1)." (PMID 39201500, 2024).
breast cancer (14 papers, 2018 to 2025). A primary or metastatic malignant neoplasm involving the breast. "Heightened expression of TRIB1 in tumor associated macrophages (TAMs) influences the breast cancer tumor microenvironment by regulating oncogenic cytokine expression." (PMID 38791967, 2024). "TRIB1 and cMYC co-amplification is further observed in breast cancer patients and associated with reduced overall and disease-free survival." (PMID 38791967, 2024). "On the other hand, TRIB1 was found to be overexpressed by tumor-associated macrophages in breast cancer, and eventually reduced T cell infiltration by inhibiting IL-15, having immune-resistant underpinnings." (PMID 39513892, 2024). "Overall, these analyses suggest the involvement of TRIB1 in response to therapy in breast cancer, and both its loss of function mutations and reduced expression levels render worse prognosis." (PMID 35664073, 2022). "In breast cancer, TRIB1 amplification is significantly associated with decreased breast cancer-specific and overall survival." (PMID 34205360, 2021). "In addition, we identified five ceRNA pairs (i.e., CDH5 with FAM212B, CDH5 with GYG2 in Module 45, TRIB1 with IL33, TRIB1 with INMT, and TRIB1 with MMRN1 in Module 110) that can be used as prognostic markers of breast cancer in BRCA-associated modules." (PMID 32256525, 2020). "TRIB1 also causes treatment resistance in cancers such as NSCLC, breast cancer, glioma, and promyelocytic leukemia." (PMID 38791967, 2024). "TRIB1 reduces DR5 protein levels in breast cancer cells through its elevated NF-кB signaling, thus decreasing TRAIL-induced apoptosis." (PMID 38791967, 2024). "A similar observation was made in breast cancer cells where knockdown of TRIB1 led to the inhibition of Akt phosphorylation." (PMID 37528172, 2023). "For example, while TRIB1 was found equally distributed between the nuclear and cytosolic fractions by Western blot in MCF7 and BT474 breast cancer cell lines, TRIB1 was mainly found in the cytoplasm of MCF7 cells in a recent report using confocal microscopy." (PMID 35205759, 2022). "In contrast, elevated levels of Trib1 in myeloid cells led to an increased late-stage mammary tumor volume, coupled with a reduction of NOS2 expressing macrophages and an overall reduction of macrophages in hypoxic tumor regions." (PMID 35664073, 2022). "Prompting us to study mammary tumor development in mice where levels of myeloid-Trib1 (mTrib1) have been genetically altered." (PMID 35664073, 2022). "In vivo models of breast cancer included immune-competent mice to characterize the consequences of altered (reduced or elevated) myeloid Trib1 expression on tumor growth and composition of stromal immune cell populations." (PMID 35664073, 2022). "Using Bayesian network inference modelling, TRIB1 expression was shown to be correlated with the levels of NF- κB and IL-8 in breast cancer, and was also considered as a potential biomarker for clinical outcomes." (PMID 35664073, 2022). "In breast cancer cell lines, TRIB1 expression was identified to regulate the cell cycle by acting upstream of the cell cycle regulator NF-κB." (PMID 35205759, 2022). "Bayesian network modelling of differentially expressed genes in breast cancer cells suppressed in the G1 phase of the cell cycle has identified TRIB1 as a novel cell cycle regulator in triple-negative breast cancer cells." (PMID 34205360, 2021). "The knockdown of TRIB1 also increased spontaneous apoptosis across a variety of breast cancer cell lines and sensitised the same cell lines to TRAIL treatment." (PMID 34205360, 2021). "Recent studies showed that CDH5 levels and CDH5 glycosylation are biomarkers for metastatic breast cancer and TRIB1 plays a critical role in cell cycle and survival via NF-κB signaling." (PMID 32256525, 2020).
breast cancer (continued). "However, in other settings, such as breast cancer, the role of TRIB1 is more nuanced, with both overexpression and knockout promoting tumor growth, making its pathogenic mechanism more complex." (PMID 40980800, 2025). "Similarly, the TRIB1 gene was identified as part of a gene signature induced in breast cancer cell lines in response to long-term paclitaxel treatment, causing treatment resistance." (PMID 38791967, 2024). "TRIB1 regulates both the G1/S and G2/M transition in breast cancer cells." (PMID 38791967, 2024). "We modelled BC growth, using these myeloid-specific mouse lines and a murine breast cancer cell line, E0771, that has recently been reported to be a luminal-B subtype 37, thus closely resembling the human BC subtype, where TRIB1 expression levels are correlated with response to chemotherapy." (PMID 35664073, 2022). "This also seems the case when we compared the interactomes of TRIB1 and -3 in breast cancer cells." (PMID 34944947, 2021). "TRIB1 knockdown has also been shown to sensitise MCF7 cells to nutlin-3 treatment and to sensitise various triple-negative breast cancer cell lines, including MDA-MB-231 cells, to TRAIL-induced apoptosis, further implicating TRIB1 in drug response in breast cancer." (PMID 34205360, 2021). "We extended this analysis to breast cancer, where we could detect a frequency of amplification in cMYC and TRIB1 greater than 15% in two independent datasets (TCGA and METABRIC)." (PMID 32932846, 2020). "We have shown the ability of TRIB3 to function as a transcriptional repressor as we looked at the similarities and differences between TRIB1 and -3 in breast cancer cells, finding new interactors that might help to understand better the function of these proteins in breast cancer pathology." (PMID 34944947, 2021). "Moreover, we discover new interactors of TRIB1 and -3 in breast cancer cells that might help to understand the role of these proteins in cancer pathophysiology." (PMID 34944947, 2021). "Recently, a characterization of TRIB1 interactome has been performed by affinity purification mass spectrometry (AP-MS) in human embryonic kidney HEK293T and breast cancer MCF7 cell lines, exhibiting known interactors, such as COP1, and new interactors." (PMID 35205759, 2022). "The transcript levels of Trib1 and Fam49b were mostly equal between MD+/+ and MD−/−, except for a reduction of Trib1 in the colon and a reduction of Fam49b in MMTV-PyVT-induced mammary tumors." (PMID 30526553, 2018). "For this we generated inducible TRIB1-tGFP and TRIB3-tGFP stable cell lines in the breast cancer cell line MCF7, a model for luminal A breast cancer, allowing immediate short-term overexpression of TRIB1 and -3, as well as control over the amount of protein being overexpressed." (PMID 34944947, 2021). "Having developed a robust AP–MS workflow to identify the interaction partners of Tribbles proteins, we wished to address the different roles of TRIB1 and TRIB3 in breast cancer, where high levels of both proteins have been reported to be associated with poor prognosis and lower survival rates." (PMID 34944947, 2021). "Thus, the roles of TRIB1 in chemotherapeutic responses in human breast cancer are critical and provide mechanistic insights into the importance of controlling myeloid TRIB 1 expression in breast cancer development." (PMID 39376611, 2024). "A similar effect was found in the breast cancer cell line MDAMB231 (a cell line which does not exhibit copy number alterations in TRIB1 according to the Cell Line Encyclopedia), thus suggesting that this might be a general mechanism of regulation." (PMID 32932846, 2020).
leukemia (14 papers, 2015 to 2023). A malignant (clonal) hematologic disorder, involving hematopoietic stem cells and characterized by the presence of primitive or atypical myeloid or lymphoid cells in the bone marrow and the blood. "Mutations in human Trib isoforms (Trib1, 2, and 3) have been associated with metabolic disease and linked to leukemia and the formation of solid tumors, including melanomas, hepatomas, and lung cancers." (PMID 33672471, 2021). "Recent studies have associated the TRIB1 gene with the development of several tumors including colorectal, leukemia, and hepatocellular cancers." (PMID 30337939, 2018). "TRIB1 (aGRP = 0.66) has been previously evidenced to be associated with tumorigeneses of various types of cancer, e.g., leukemia and colorectal cancer." (PMID 30390627, 2018). "This analysis pointed out an overexpression of TRIB1.TRIB1 is a pseudokinase that has been implicated in the development of leukemia andalso metabolic disorders." (PMID 29599769, 2018). "First, Trib1 has been well characterized as a proto-oncogene that stimulates proliferation of leukemia cells." (PMID 37355685, 2023). "TRIB2 (and TRIB1) expression promotes AML in HOX-dependent leukaemias, and in acute promyelocytic leukaemia (APL)." (PMID 29599919, 2018). "Furthermore, overexpression of TRIB1 reduced C/EBPα protein levels, resulting in progression of leukemia in murine models." (PMID 37773170, 2023). "Amongst those, two genes Egr1 and Trib1 stood out because of their known involvement in leukemia." (PMID 37532789, 2023). "Despite its well-known role in leukemia and M2 macrophages, the physiological role of TRIB1 in the adipose tissue remains unclear." (PMID 34811364, 2021). "In fact, TRIB1 has been described as a myeloid oncogene due to its strong link with leukemia." (PMID 30337939, 2018). "Despite being capable of driving myeloid leukemia when overexpressed alone, it is assumed that cooperating lesions occur in TRIB1 and TRIB2 mouse leukemia models." (PMID 27908682, 2017). "Overexpression of TRIB1 has been also linked to leukemia and, while BRD0418 has limited effects on non-hepatic cells and the potency of TRIB1 as an oncogene has not yet been fully evaluated, the oncogenic potential of TRIB1 inducing agents will need to be closely monitored in future animal studies." (PMID 25811180, 2015). "The hypothesis that TRIB1 and PML/RARA cooperate has been tested and, while they do not cooperate to drive a shorter latency leukemia in vivo, TRIB1 and PML/RARA have functionally redundant inhibitory effects on C/EBPα, which also impacts responses to therapeutic All-Trans Retinoic Acid (ATRA)." (PMID 27908682, 2017).
atherosclerosis (13 papers, 2011 to 2026). A disease characterized by the build-up of fatty material and calcium deposition in the arterial wall resulting in partial or complete occlusion of the arterial lumen. "This study evaluates the associations of TRPS1 and TRIB1 polymorphisms with subclinical atherosclerosis (SA) and plasma lipid levels in Mexican individuals." (PMID 41972583, 2026). "A signal near TRIB1 (lead SNP rs112875651) colocalises with hyperlipidaemia and atherosclerosis and has been linked to lipid levels in previous studies, and SNPs in this gene have an established role in the development of NAFLD." (PMID 34128465, 2021). "Furthermore, CBT was explored for its anti-atherosclerosis capability by performing docking analysis on the TRIB1 protein, which is known to cause early atherosclerosis." (PMID 37928840, 2023). "Genetic deletion of TRIB1 promotes atherosclerosis in mice, which is accompanied by pronounced hyperlipidemia and hepatic and systemic inflammation." (PMID 38791967, 2024). "Using the energy-optimized structure, the CBT was subsequently docked with TRIB1 protein to analyze its anti-atherosclerosis properties." (PMID 37928840, 2023). "TRIB1 regulates polarization of macrophages and dysregulated Trib1 expression in murine models has been shown to alter atherosclerosis burden and adipose homeostasis." (PMID 33329538, 2020). "In summary, we have confirmed the proatherogenic impact of myeloid TRIB1 in two distinct in vivo models of human atherosclerosis." (PMID 31692955, 2019). "One of the most notable outcomes arising from roughly doubling Trib1 expression in macrophages was the increase in foam cell size that developed in both of our models of human atherosclerosis." (PMID 31692955, 2019). "TRIB1 has previously been shown to be a key regulator of multiple inflammatory factors and immune cell function, influencing pathologies with an inflammatory component including cancer and atherosclerosis." (PMID 38896446, 2024). "TRIB1 is an established oncogene in acute myeloid leukemia and has been shown to play a pivotal role in the differentiation of anti-inflammatory M2-macrophages in the pathogenesis of early atherosclerosis and during adipose tissue inflammation." (PMID 33329538, 2020). "An in vitro study suggested that the protein product of TRIB1 is in control of vascular smooth muscle cell proliferation and consequently may drive the development of atherosclerosis." (PMID 24922540, 2014). "Trib1 controls atherosclerotic plaque macrophage function by up-regulating OLR1, promoting foam cell formation and atherosclerosis." (PMID 31692955, 2019). "Furthermore, TRIB1 was found to play an essential role in CAD and atherosclerosis through its overexpression." (PMID 37147786, 2023). "However, lack of TRIB1 in myeloid cells decreases early atheroma formation and reduces atherosclerosis burden in mouse models." (PMID 38791967, 2024). "However, the exact mechanism of TRIB1 in the development of atherosclerosis is still not known." (PMID 25986010, 2015).
acute myeloid leukemia (12 papers, 2012 to 2025). Acute myeloid leukemia (AML) is a group of neoplasms arising from precursor cells committed to the myeloid cell-line differentiation. "This functional role of TRIB1 has been the key association of TRIB1 in regulating appropriate myeloid cell differentiation, and consequently, dysregulation of this molecular mechanism is understood to play a role in the development of acute myeloid leukemia." (PMID 35205759, 2022). "In acute myeloid leukemia, high BCL11A expression is associated with a poor response to chemotherapy and promotes the proliferation and engraftment of TRIB1-expressing acute myeloid leukemia cells in vitro and in vivo." (PMID 39857257, 2025). "Considerable research interest in TRIB1 has focused on its role in the development and progression of acute myeloid leukemia and Down syndrome-related megakaryocytic leukemia." (PMID 35205759, 2022). "The most well-understood role of TRIB1 is in acute myeloid leukaemia, where it can regulate C/EBP transcription factors and kinase pathways." (PMID 34205360, 2021). "In addition, RFWD2 accelerates the development of Trib1- and Trib2-induced acute myeloid leukemia in mouse models, which is abrogated when Rfwd2 or Trib1/2 is deleted or mutated." (PMID 34646775, 2021). "TRIB1 has different states that could potentially be targeted by small-molecule inhibitors and well-established relevance in acute myeloid leukaemia through degradation of transcription factors." (PMID 34205360, 2021). "TRIB1 has also beenimplicated as a key oncogene in acute myeloid leukaemia and ovarian cancers." (PMID 26678268, 2015). "In 32%, we found an amplification of 8q24.13 containing TRIB1 (qG2.0 = 6.7 × 10−6) that is also amplified in acute myeloid leukemia (AML) and is known to induce MEK1/ ERK signaling." (PMID 34465776, 2021).